IL10 (interleukin 10)
Diseases named in the same sentence as IL10 in open-access papers (continued):
Sharing a sentence is not in itself a finding about the gene and the disease.
infection (continued). "In fact, IL-10 genetically deficient mice showed higher mortality due to a change in the Th1 profile after infection by T. cruzi, with increasing levels of TNF-α and IFN-γ in cardiac tissue." (PMID 34215249, 2021). "We observed an enhancement of lung P. aeruginosa clearance at 24 h post infection, associated with the decrease of chemokines and proinflammatory cytokines, the restoration of IL-10 and a reduction in neutrophil recruitment." (PMID 34182930, 2021). "The results we found for IL10 are seemingly contradicting when looking at the protective effect for IL10 − 1082 *G in the susceptibility to CT infection versus the risk and role of the IL10 − 1082 GG genotype in the severity of a CT infection." (PMID 33430411, 2021). "B cells also produce IL‐10,135 and overall IL‐10 production is lower in B1 B‐cell‐deficient mice early during infection." (PMID 32799361, 2021). "For the further endpoints of interest, associations were observed in all patients for IL37 rs2723186 with CMV disease, for IL10 rs1800872 with the occurrence of graft loss or death, and for IL10 rs3024496 with the occurrence of infections." (PMID 33861738, 2021). "Instead, B. microti causes a sustained increase in the levels of serum IL-10, which plays a major role in the resolution of infection." (PMID 32411624, 2020). "We had previously shown that MDDCs exposed to Env of TFs secreted higher levels of IL-10 than those stimulated with Env isolated from variants during chronic stages of infection (CI)." (PMID 32615983, 2020). "The underlying mechanism probably involves the induction of IL-10-producing cells early in the infection and modulation of dendritic cell maturation." (PMID 32776984, 2020). "Infection of DCs was associated with enhanced expression of surface markers and proinflammatory cytokines, while inhibiting proliferation of T cells through IL-10." (PMID 33708193, 2020). "Bacterial loads in the lung homogenates were comparable between WT and IL-10-deficient mice 1 day after infection." (PMID 32153580, 2020). "IgMi mice were susceptible to a high-dose infection, with reduced Th2 cytokines and elevated B cell-derived IL-10 in mesenteric lymph nodes (MLN) compared to controls." (PMID 32778925, 2020). "BMDMs differentiated from TLR4-deficient mutant mice produced more IL-10 after Mtb strain HN878 infection than after H37Rv infection." (PMID 32403973, 2020). "Many immunoregulatory molecules and pathways, most notably those associated with interleukin-10 (IL-10) production, are activated following infection, which can suppress antiparasitic CD4+ T cell functions." (PMID 32908913, 2020). "Of note, deficiency in IL‐10, is associated with more rapid resolution of some infection and clearance of intracellular pathogens." (PMID 32889775, 2020). "Six days post-infection, C. concisus infection in IL-10−/− mouse colon caused a decrease in the amiloride-sensitive ISC when compared with control mice, indicating marked ENaC dysfunction." (PMID 31936044, 2020). "WT or IL-10-deficient BMDMs (1 × 105 cells/animal) were adoptively transferred into WT and IL-10-deficient recipient mice through an intranasal route 24 h before infection." (PMID 32153580, 2020). "Antiinflammatory cytokines (IL-10) were positively associated with infection and poor delivery outcomes." (PMID 32365058, 2020). "After correction for sex, age and infection status at study onset, high levels of parasite-specific IL-10 were recognised as a risk factor for re-infection in a study conducted in Gabon." (PMID 34485462, 2020). "Systemically, circulating concentrations of the immune mediators S100A12 and IL-10 change in the context of ICAM-1 during an infection, and these changes are specific to the causative otopathogen." (PMID 32595639, 2020). "In this study, A. baumannii induced STAT3 phosphorylation in WT BMDMs starting 2 h after infection, a process which was impaired in IL-10-deficient macrophages." (PMID 32153580, 2020).
infection (continued). "Remarkably, A. baumannii strongly induced STAT3 phosphorylation in WT macrophages after 2 h of infection but was reduced in IL-10-deficient cells." (PMID 32153580, 2020). "Many inflammatory cytokines and chemokines such as IL-6, IL-1β, IL-8, CCL8, CXCL9, CXCL16, MCP-1 and IP-10 and immunosuppressive cytokines such as IL-10 are elevated in both infections and associate with clinical disease severity." (PMID 33199778, 2020). "In contrast to a global IL-10 deficiency, the current study associates the presence of B cell-derived IL-10 with susceptibility to infection and a compromised Th2 immune response." (PMID 32778925, 2020). "In the BALB/c model, several lines of evidence suggest that the control of infection depends not only on the induction of IFN-γ-mediated responses but also on the control of IL-10 and IL-4 cytokines that are associated with pathology." (PMID 32630347, 2020). "IL-4 and IL-10 are key regulators of the immune response and downregulate Th1 response-driven inflammatory reactions, protecting the host from infection-associated immunopathology to maintain placental homeostasis." (PMID 32552750, 2020). "IL-10 is associated with limiting resistance to infection against M. tuberculosis and inhibiting Th1 immune response." (PMID 33396862, 2020). "This suggests that reducing NHERF1 is an ideal target for regulating infection/inflammation-associated preterm labor as it can downregulate NF-kB and increase IL-10." (PMID 33092043, 2020). "The activity of myeloperoxidase (MPO), mostly expressed in neutrophils, was also significantly increased in the lung homogenates of IL-10-deficient mice with A. baumannii infection at 1 and 3 days after infection." (PMID 32153580, 2020). "The transposon library was generated in a flagellin-negative Δhly background (ΔhlyΔfla) to eliminate the identification of false low-IL-10 mutants resulting from mutations in flagellar components that reduce infection efficiency." (PMID 32634175, 2020). "IL-10 mRNA transcripts were found to be upregulated in the spleen and small intestine of susceptible chickens after infection with E. maxima." (PMID 32175341, 2020). "Animals deficient in either of the pro-Th1 factors IL-12 or IFN-γ, or the regulatory cytokine IL-10, are more susceptible to die of P. chabaudi infection, even though it is a normally mild infection in mice." (PMID 32634740, 2020). "Underexpression of Th2 cytokines, such as IL4/IL13, as well as IL10 and TGFβ, which are primarily associated with tissue repair and extracellular matrix composition, was observed during the late stage of infection, especially in infected fish at 11°C." (PMID 32695119, 2020). "Next, to explore the functional role of Malat1/Maf/IL-10 pathway in vivo, we studied the role of Malat1 in infection models in which IL-10 deficiency either promotes pathogen clearance or enhances immunopathology." (PMID 32321759, 2020). "IL-10 has, however, been recognised to be immunosuppressive and we recently found that it was reportedly more upregulated in relevant tissues following infection with key poultry pathogens in more susceptible vs. more resistant chickens." (PMID 31100860, 2019). "MDM-infection assays using 2:1 or higher MOIs report upregulation of IL-10, IL-6, and tumor growth factor (TGF)-β, cytokines associated with suppression of cell mediated immunity." (PMID 31614819, 2019). "In contrast to IL-6, increased IL-10 expression counteracts T cell responses, enhances injury-associated immunosuppression, and increases susceptibility to infection." (PMID 31152269, 2019). "The impairment of CCL19/CCL21 chemokines in C57BL/6 mice infected with L. donovani results in reduced activation and mobility of DCs in the spleen, and elevated levels of IL-10 mRNA that correlates with higher susceptibility to infection." (PMID 31847221, 2019). "In Balb/c mice, IL-10 is associated with the phenomena of susceptibility to infection by intracellular microorganisms, such as Leishmania major." (PMID 31131262, 2019).
infection (continued). "The infection of recombinant SFTSV possessing NSs with a mutation at the amino acid position 102 from proline to alanine (NSs-P102A) reduced the expression of IL-10." (PMID 31547199, 2019). "In this work, severe infection was associated with significant hemozoin accumulation, elevated transcripts for Ifng, Il10, and Mgl2, a marker for monocyte/macrophages in conceptuses, and reduced maternal vascular space in the placenta." (PMID 31862902, 2019). "In the present study, the early-life GOS intervention did not affect the mRNA expression of IL-8, but significantly increased the mRNA expression of IL-10 on day 21, suggesting a decreased susceptibility to infection by pathogens." (PMID 31366090, 2019). "Our data, along with previous data from an HSV encephalitis model, suggest that IL-10 plays a central role in mediating protection against the inflammation associated with infection." (PMID 30909599, 2019). "Based on our results and the information reported in the literature, we believe that IL-10 produced by B-1CDP cells is the key to understanding their increased susceptibility to infection." (PMID 31338088, 2019). "Here the binding of bacterial lipopolysaccharides (LPS) to the maternal-derived virus caused the production of immunosuppressive IL-10 in the pups and this facilitated their infection." (PMID 31636623, 2019). "The cytokine IL-10 is known to function in the host immune response to infectious disease and shown to over-ride the host inflammatory responses to infection, meaning it is closely associated with microbial persistence." (PMID 31338112, 2019). "Deficiency of IL-10 improved the anti-virus ability of the mice at the early phase of infection through increasing either pro-inflammatory cytokines’ (IL-2, IL-6, IL-12, TNF-α, IFN-α, IFN-γ) production or PCV2-specific antibodies." (PMID 31551984, 2019). "IL-10 plays pleiotropic roles in defense against infection depending on the illness and the causal pathogen." (PMID 31776239, 2019). "Addressing the nationality, a study showed that the IL-10; rs1800872 was associated with the increased risk of infection with influenza A/H3N2 virus in Iranian population." (PMID 31196204, 2019). "Inhibition of cNOS during infection caused higher IL-10 production in the wild-type group and increased IFN-γ levels in knockout mice suggesting a change in cytokine profile upon cNOS absence for both mouse groups." (PMID 31772504, 2019). "On the other hand, regulatory cytokines, such as IL-10, are required to limit the response against N. caninum, protecting the host from infection-associated immunopathology." (PMID 31114577, 2019). "In experimental VL, IFN-γ and IL-12 cause the protective condition while IL-4 and IL-10 enhance the progression of infection." (PMID 30834079, 2019). "In perforin-deficient mice that show a more sustained infection, NK cells produce more sustained levels of IL-10." (PMID 31803193, 2019). "Ma.24 infection caused the down‐regulation of IL‐10 which was further decreased by HMGN2 knock‐down in macrophages, while we observed that there is no obvious influence by Ma.24 infection and HMGN2 knock‐down on TGF‐β expression in macrophage." (PMID 31596045, 2019). "The expression of Interleukin-10b (il10b), the paralog of il10a, was induced by the infection, but similarly in susceptible and resistant fish." (PMID 31878870, 2019). "These assays suggest that B-1cells are a very important source of IL-10, which is able to modulate macrophages to become more susceptible to infection by T. cruzi." (PMID 31338088, 2019). "Murine model of VL demonstrates higher disease susceptibility due to the presence of high IL-10 levels during initial phase of infection." (PMID 31024534, 2019). "Whereas during infections caused by extracellular or highly inflammatory bacteria, IL-10 production reduces host tissue damage and facilitates host survival." (PMID 30279680, 2018).
infection (continued). "The high concentration of IL-10 during the acute phase is associated with failed control of infection, and as shown here, EV Y altered the balance between the pro-inflammatory/regulatory cytokines toward an immunoregulatory profile." (PMID 29755471, 2018). "MHV-68 infection is reported to cause GI dilatation and bacterial overgrowth in interleukin-10 (IL-10)-deficient mice, but GI dilatation in MHV-68 infection is not well understood and has not previously been reported in WT or IFNγR−/− mouse models." (PMID 30249047, 2018). "Increased peripheral levels of IL-4 and IL-10 have also been described in Neospora caninum infected cattle, but are thought to be associated with a decreased ability of the host to control infections with coccidia." (PMID 29973271, 2018). "Considering the different phenotypes under the infection of M. incognita and identifying the key features of resistance, divergent patterns of expression between resistant IL10–1 and susceptible CC3 were the focus." (PMID 30075750, 2018). "In a murine IL-10 deficient models of infection, an increased presence of CD8+ and CD4+ T cells in inflammatory cardiac infiltrates, albeit with the exception of Treg cells, which have a decreased frequency." (PMID 30197647, 2018). "The genes encoding the regulatory cytokines IL-10 and IL-33 were also expressed principally in MΦs before infection and upregulated after infection." (PMID 29408905, 2018). "The crucial role of IFN-γ and IL-10 during infection was further substantiated using gene-deficient mice, where the absence of IL-10 coincided with high pathology and early mortality." (PMID 29497418, 2018). "At a later stage of the infection, the observed transition is associated with high levels of Th2 cytokines, such as IL-4, IL-10, TGF-β, and IL-13, which correlates with disease severity." (PMID 30283745, 2018). "In mice with T cells deficient in the regulatory cytokine IL-10 (IL-10 KO), infection with Plasmodium chabaudi leads to a hyper-inflammatory response and lethal outcome that can be prevented by anti-TNF treatment." (PMID 29866139, 2018). "Overall, during infections caused by intracellular bacteria or by pathogens that modulate the inflammatory response, IL-10 production facilitates bacterial persistence and dissemination within the host." (PMID 30279680, 2018). "High IL-10 levels are mainly associated with active infectious uveitis and considered to be important in early stage of infection." (PMID 29944680, 2018). "On the other hand, susceptibility to infection is associated with the production of IL-10 and transforming growth factor beta (TGF-β)." (PMID 29743880, 2018). "This review discusses the current data about the role of IL-10 during infections caused by major circulating antibiotic resistant bacteria." (PMID 30279680, 2018). "The analysis showed that allergic reactivity was inversely associated with the presence of infection and positively associated with low (≤100 pg/ml) serum concentration of IL-10 and high (>100 pg/ml) concentration of IL-33." (PMID 30713536, 2018). "Important is that when the role of T cells and IFNγ are considered within a trypanosomosis context, IL-10 was shown to be the main counter regulator of infection-associated inflammation in both T. brucei and T. congolense models." (PMID 30333827, 2018). "Higher post-operative Interleukin-10 mRNA (P = 0.007) and protein (P = 0.001) levels were associated with an increased risk of infection." (PMID 30212506, 2018). "Specifically, M1-like associated gene IL-1β was significantly increased in cells after class II strain LaSota infection, whereas M2-like associated gene IL-10 was only upregulated in class I strain F55-infected cells." (PMID 29670609, 2018). "IL-10 production rapidly increased during DENV-ADE infections, and cell-type specificity and genetic polymorphisms of hosts affect IL-10 production." (PMID 29740424, 2018).
infection (continued). "Unexpectedly, the number of classical CD4+Foxp3+ Tregs producing IL-10 was similar in the cardiac tissue of Ebi3-deficient and WT mice at day 15 after infection, suggesting that Ebi3 was unable to promote the development of classical Tregs." (PMID 29033934, 2017). "TLR3-deficient DCs produced strikingly less TNF-α and IL-10 and exhibited a slight increase in IL-23 secretion 12 hours after infection." (PMID 28973047, 2017). "When IL-10 knockout mice were infected with P. gingivalis via oral lavage, IL-10−/− mice exhibited three fold more bone loss in comparison with WT mice after infection with P. gingivalis." (PMID 29163477, 2017). "Enhanced secretion of IL-10 has been reported to increase susceptibility of mice to infections by mycobacterial and fungal pathogens." (PMID 28791019, 2017). "On the other hand, the IL-10-modulated pattern elicited by TcI-derived antigen provides evidence of susceptibility to infection with this genotype." (PMID 28225764, 2017). "The production of IL-10 is necessary for the host, in order to reduce the immune pathology otherwise associated with infections, but an excess also reduces the effectiveness of immune control." (PMID 28628650, 2017). "Accordingly, IL-10−/− mice that received T cells showed a significant increase in clinical score and weight loss starting day 7 post infection, as compared to uninfected mice and mice that received IL-10-producing DCs and macrophages." (PMID 28824622, 2017). "There was clear evidence that the IL-10 rs1800872 and rs3021097 genotypes have an association with the decreased risk of infection in lung transplant recipients." (PMID 28246425, 2017). "In our cohort, both IFNγ/IL10 coproducing and IL10 single-producing subsets were associated parasite density during recent infection, while only IL10 single-producing responses were associated with protection from symptomatic disease." (PMID 29097996, 2017). "In summary, our study has identified the cellular origins of IL-10 during M. tuberculosis infection in vivo and their specific contribution to host susceptibility to infection." (PMID 28584007, 2017). "Adjusted logistic regression analysis of our data indicated that infections were not only associated with serum levels of IL-10, but also correlated with splenic volume, leukocyte counts, the percentage of Treg cells, and serum levels of CRP and IFN-γ." (PMID 27682880, 2017). "IL-10 is a key component of this cytokine system that regulates and suppresses the expression of proinflammatory cytokines during the recovery phases of infections and consequently reduces the damage caused by inflammatory cytokines." (PMID 28316998, 2017). "In contrast, challenge with large numbers of parasites in the footpad of BALB/c mice generates a progressive infection associated with parasite-specific responses mediated by IL-10 and IL-4." (PMID 28558043, 2017). "HIV-infection is characterized by a Th1 to Th2 cytokine shift during the course of the infection which includes an enhanced potential for robust IL-10 and associated Treg response." (PMID 28143443, 2017). "IL-12 and TNF possess potent anti-viral property and also promote macrophage activation, while IL-10 plays an important cross-regulatory role during infection associated inflammation." (PMID 28067803, 2017). "In contrast, this balance is skewed in favor of IL-10 production in individuals with DM who are most at risk of infection." (PMID 28216665, 2017). "Host immune parameters such as the magnitude of interferon gamma and interleukin-10 responses have been implicated in the outcome of infection." (PMID 28934262, 2017). "High levels of IL-10 production have been described in active and chronic CL, while low cytokine levels have been related to self-healing and asymptomatic infection caused by L.V." (PMID 28241747, 2017). "We found that IL-10 production was significantly reduced in the myocardium of Ebi3-deficient mice compared to WT mice at day 15 after infection." (PMID 29033934, 2017).